FAM24B (family with sequence similarity 24 member B)
Synonyms: MGC45962; AC073585.2
Tractability: Antibody: UniProt places it where antibodies can reach, with high confidence; UniProt predicts a signal peptide or a membrane-spanning region; its Gene Ontology location is reachable by antibodies, with medium confidence. PROTAC: ubiquitination databases record sites on it.
Gene: Protein-coding gene on chromosome 10 (122,849,078 to 122,879,641, reverse strand). Ensembl gene ENSG00000213185.
Subcellular location: Secreted
Gene Ontology:
Molecular function: protein binding
Cellular component: extracellular region
Genetic constraint (gnomAD): Loss-of-function variants: 1 observed, 1.35 expected, observed/expected ratio (o/e) 0.74, 90% interval 0.22 to 1.86. That is too few expected variants to judge how well the gene tolerates losing a copy. Missense variants: 93 observed, 112.35 expected, observed/expected ratio (o/e) 0.83, 90% interval 0.7 to 0.98. Synonymous variants: 33 observed, 42.44 expected, observed/expected ratio (o/e) 0.78, 90% interval 0.59 to 1.04.
Homologues: Orthologues: chimpanzee FAM24B (96% identical). Paralogues in human: FAM24A (70% identical).